H2AX (H2A.X variant histone)
Diseases named in the same sentence as H2AX in open-access papers (continued):
Sharing a sentence is not in itself a finding about the gene and the disease.
small cell lung carcinoma (1 paper, 2018). Small cell lung cancer (SCLC) is a highly aggressive malignant neoplasm, accounting for 10-15% of lung cancer cases, characterized byrapid growth, and early metastasis. "The Sry/miR138/H2AX axis may be involved in the regulation of small cell lung cancer, thereby possessing potential diagnostic and therapeutic intervention values." (PMID 30400981, 2018). "In small cell lung cancer cells, miR-138 targets H2A histone family member X (H2AX) and regulates DNA damage responses." (PMID 30400981, 2018). "It has been hypothesized that miR-138 targets H2AX and affects the proliferation and cell cycle progression of small cell lung cancer cells through inhibiting H2AX expression." (PMID 30400981, 2018).
soft tissue sarcoma (1 paper, 2017). A malignant neoplasm arising from muscle tissue, adipose tissue, blood vessels, fibrous tissue, or other supportive tissues excluding the bones. "Initially, we demonstrated that in bone and soft tissue sarcoma (BSTS) cell lines trabectedin treatment significantly increased phosphorylated histone H2AX (P-H2AX), the marker of DNA double-strand breaks (p < 0.001)." (PMID 28454547, 2017).
steatosis (1 paper, 2012). Increased lipid within the cytoplasm of cells. "The significant changes in proteome profile in chronic ethanol binge were accompanied by a marked increase in liver injury as evidenced by enhanced steatosis, necrosis, increased 4-hydroxynonenal labeled proteins, CYP2E1 expression, and decreased histone H2AX phosphorylation." (PMID 22545783, 2012).
Stroke (1 paper, 2022). Sudden impairment of blood flow to a part of the brain due to occlusion or rupture of an artery to the brain. "Although experimental stroke produces DNA damage, we established a rat stroke model and used immunohistochemistry for the detection of γ-H2AX, a marker of DNA damage." (PMID 36034843, 2022).
T-cell lymphoma (1 paper, 2016). "Surprisingly, the same pattern of γ-H2AX that coincided with the profile of DSBs was observed in actively proliferating Jurkat cells (T-cell lymphoma culture cells)." (PMID 27160357, 2016).
type 1 diabetes (1 paper, 2023). "Besides, ATM protein was expressed in ɣ-H2AX-expressing testicular cells and could participate in histone phosphorylation in type 1 diabetes." (PMID 38027164, 2023).
Ureteral obstruction (1 paper, 2023). Obstruction of the flow of urine through the ureter. "In in vivo experiments in mice, acetate treatment significantly ameliorated fibrosis induced by unilateral ureteral obstruction, and the oxidative stress marker phosphorylated histone H2AX (γH2AX) was also reduced." (PMID 37463875, 2023).
varicocele (1 paper, 2024). A condition characterized by the dilated tortuous veins of the spermatic cord with a marked left-sided predominance.
vitamin D deficiency (1 paper, 2012). A nutritional condition produced by a deficiency of VITAMIN D in the diet, insufficient production of vitamin D in the skin, inadequate absorption of vitamin D from the diet, or abnormal conversion of vitamin D to its bioactive metabolites. "The results of our analysis showed a significant (p = 0.023) 50% increase in γ-H2AX foci/cell (5.99±0.90 vs. 4.00±0.27) in cells from patients with vitamin D deficiency, suggesting a protective role for vitamin D against DNA damage in a clinical setting." (PMID 23029205, 2012).
Werner syndrome (1 paper, 2015). "A similar observation was reported in a study examining lymphocytes from 21–72 years old, incidence of endogenous γ-H2AX foci increased with age until ~50 years old and were considerably higher in age matched Werner syndrome patients." (PMID 25794041, 2015).
tumor (446 papers, 2003 to 2026). "In this manuscript, we have shown a role for the histone H2AX in replication fork biology in BRCA1/2-deficient tumours." (PMID 38789420, 2024). "Together, these data indicate that ATM inhibitors in combination with PARPi can be effectively used to overcome drug resistance in H2AX-deficient tumours and control tumour growth." (PMID 38789420, 2024). "In summary, our results demonstrate a role for H2AX in replication fork biology in BRCA-deficient tumours and establish a function of H2AX separable from its classical role in DNA damage signalling and DSB repair." (PMID 38789420, 2024). "Although anecdotal, this case indicates that H2AX loss is a clinically relevant mechanism associated with chemotherapy resistance in BRCA-deficient tumours." (PMID 38789420, 2024). "Here, the authors identify a role of γH2AX in the degradation of replication forks and demonstrate that H2AX loss drives PARP inhibitor resistance via increased stressed fork stability in BRCA-deficient tumours." (PMID 38789420, 2024). "Thanks to the molecular characterization of the mechanisms behind the stabilization of stressed forks, we also identified an acquired genetic vulnerability of H2AX-deficient tumours, which is the inhibition of the ATM kinase." (PMID 38789420, 2024). "High expression levels of TRIM28, H2AX or CDK4 were significantly associated with tumor recurrence in an independent cohort of HCC." (PMID 37870748, 2023). "H2AX is a variant of histone H2A, and its expression levels significantly differ in various cell lines and tumor tissues." (PMID 35903980, 2023). "H2AX has been reported to be associated with tumor size, vascular invasion, TNM stage and reduced survival after HCC transplantation." (PMID 37870748, 2023). "Our in vitro assay reproduced the PARPi sensitivity of the inherited 2 bp duplication, and RAD51D and γ-H2AX foci formation assays confirmed that deficient HR repair existed in the first surgery tumor sample." (PMID 37833926, 2023). "The HBV/HCV/alcohol-associated Tumor tissues studied had reduced H2AX but higher gammaH2AX protein levels providing evidence of increased DNA damage during liver disease progression." (PMID 35804458, 2022). "Therapeutically, 195mPt-BP treatment causes 4.5-fold more γ-H2AX formation, a biomarker for DNA damage in metastatic tumor cells compared to 195mPt-cisplatin." (PMID 33490949, 2021). "Conversely, tumor expression of γ-H2AX was associated with nuclear Cyclin E (β = 0.407, P < 0.001) and with cytoplasmic Cyclin E (β = 0.324, P < 0.001)." (PMID 32964114, 2020). "In unirradiated tumours, an observed increase in hypoxia was associated with higher levels of γ-H2AX staining when compared to irradiated tumours that showed lower PIMO staining." (PMID 31109312, 2019). "The anti-tumor effect of PDMP in mouse xenografts can be determined by assessing the expression of tumor-associated γ-H2AX, which represents the level of DNA damage." (PMID 29416613, 2018). "The effect of deoxyribonucleic acid (DNA) damage in experimental groups can be determined by assessing the expression of tumor-associated γ-H2AX." (PMID 28797171, 2017). "We have used the assay to correlate baseline γ-H2AX levels with the robustness of DNA damage response, as well as to reveal a potential relationship between % γ-H2AX and tumor mutational load." (PMID 28158293, 2017). "We report here that increased γ-H2AX expression in HCC is associated with tumor size, vascular invasion, TNM stage and reduced survival rate after liver transplantation (LT)." (PMID 25537504, 2015). "Once activated, the Br-IPM moiety can efficiently induce intramolecular 1′ 3′-cross-linkage of DNA, resulting in S139 phosphorylation of histone H2AX and ultimately causing tumor cell death." (PMID 25254649, 2014).
tumor (continued). "This was associated with a strong increase in the levels of γ-H2AX and cleaved caspase-3, indicating that tumour cells were undergoing apoptosis, most likely due to excessive DNA damage." (PMID 24092664, 2013). "Furthermore, in the attempt to discover acquired genetic vulnerabilities, we find that ATM but not ATR inhibition overcomes PARP inhibitor (PARPi) resistance in H2AX-deficient tumours by interfering with CtIP-mediated fork protection." (PMID 38789420, 2024). "Importantly, we identify a role of H2AX in modulating replication fork stability which appears to contribute to the sensitivity of BRCA-deficient tumours to PARPi." (PMID 38789420, 2024). "Interestingly, IHC staining on tumor sections evidenced a reduction of the proliferation marker Ki-67 and increased expression of senescence-associated markers p16, H2AX, pHP1-γ and PAI-1 on mice infused with VSSP-BMDMs." (PMID 37055829, 2023). "Our findings shed light on the potential engagement of DDR genetic aberrations and the clinicopathologic relevance of the heightened expression of γ-H2AX and 53BP1 in GISTs, which represent useful biomarkers of aggressiveness in tumor evolution and aid in distinguishing cases at risk of progression." (PMID 35406559, 2022). "However, UM-SCC47 or MDA-MB-231 tumor cells arrested in response to SSTNEGFR fail to activate either Chk1 or Chk2 or cause phosphorylation of H2AX (γH2AX)." (PMID 35569509, 2022). "Finally, the analysis of HCC1806_sh6 xenograft tumors by immunofluorescent staining revealed that MLK4 knock-down was associated with persistent H2AX phosphorylation in tumor tissues after the treatment with doxorubicin in vivo." (PMID 34839359, 2021). "AgNPs are considered tumor initiators because AgNP-induced γ-H2AX generation may result from oxidative DNA damage caused by increased intracellular oxidation." (PMID 30813344, 2019). "Furthermore, utilizing the NCI-60 human tumor cell lines, we show that there is a correlation between the baseline fraction of phosphorylated H2AX and mutational load in the various cell lines." (PMID 28158293, 2017). "If future studies continue to support a correlation between % γ-H2AX and protein function-affecting gene mutations, % γ-H2AX measured by the sandwich ELISA method could potentially be explored as an indicator of tumor mutational load." (PMID 28158293, 2017). "In conclusion, our data indicate that successive cycles of chemotherapy in TN patients drive a chronic oxidative stress reaction associated with reduced levels of total H2AX protein, the extent of which could sensitize tumour cells to chemotherapy." (PMID 27006338, 2016). "Interestingly, the decrease in H2AX protein is associated with high rate of tumour cell apoptosis and thus indicative of response to treatment and patient survival, in one of the most aggressive forms of BC, the Triple‐Negative (TN) BC subtype." (PMID 27006338, 2016). "In addition, the ectopic expression of rpL3 either in untreated cells or treated cells induced γ-H2AX formation strongly suggesting that rpL3 exterts itself cytotoxic effects leading to increase the susceptibility of tumor cells to chemotherapy." (PMID 25473889, 2014).
tumor (continued). "γ-H2AX has been demonstrated to be positively associated with tumor radiosensitivity." (PMID 24137315, 2013). "In addition to these cell cycle regulators, silencing the expression of SENP1 also significantly increased IR-induced γ-H2AX expression, which has been revealed to be positively associated with tumor radiosensitivity." (PMID 24137315, 2013). "γ-tocopherol-rich mixture of tocopherols (γ-TmT, considered as vitamin E) significantly lowered tumor multiplicity, tumor volume, and tumor burden, which was associated with high apoptosis and low levels of 8-hydroxydeoxyguanine, γ-H2AX and nitrotyrosine in the NNK-induced lung." (PMID 21559252, 2011). "The distinctheterogeneity in the numbers of γ-H2AX foci in these tumor cell lineswas found to be due to foci associated with uncapped telomeres, and theamount of total telomeric damage also appeared to inversely correlate withthe telomerase activity present in these cells." (PMID 20157510, 2009). "Finally, we explored whether ATMi restores PARPi sensitivity also in H2AX-deficient tumours in vivo." (PMID 38789420, 2024). "IHC staining demonstrated that the combination treatment enhanced tumor growth inhibition and DNA damage, as indicated by decreased Ki67 staining and increased γ‐H2AX signal." (PMID 41114465, 2026). "Conversely, genes linked to DNA-damage responses and apoptotic pathways (H2AX, DAXX, ANXA1) demonstrated relatively higher expression in prehabilitation-treated tumor regions." (PMID 41596590, 2026). "In vivo, Epacadostat and Olaparib significantly suppressed MDA-MB-468 tumor growth compared to the monotherapy groups, while promoting an increase in phosphorylated H2AX." (PMID 41900138, 2026). "Concurrently, the proportion of γ-H2AX+ cells in the tumor tissues was substantially decreased, indicating that most cells had completed the DNA damage repair process." (PMID 41055972, 2025). "In low‐grade tumours, the immunoreactivity for H2AX and 8‐OHdG was weak, and the expression of CASP‐3 was strong." (PMID 40569274, 2025). "Counting the γ-H2AX-positive cells per HPF allows for a quantitative assessment of the level of DNA damage within the tumor." (PMID 40723820, 2025). "Phosphorylation of histone H2AX facilitates recruitment of DNA damage response proteins, promoting tumor microenvironment remodeling and immune evasion." (PMID 39991629, 2025). "In the immunofluorescence examination, severe intracytoplasmic Nop10 and H2AX expressions were found in neurons around the tumor mass." (PMID 39821858, 2025). "In the immunofluorescence examination, severe intracytoplasmic Nop10 and H2AX expressions were detected around the tumor mass." (PMID 39821858, 2025). "In the immunofluorescence examination, moderate Nop10 and H2AX expressions were identified in neurons around the tumor mass in B2 group." (PMID 39821858, 2025). "The trial also aimed to assess biochemical changes in PARP and H2A histone family member X (H2AX) activity in mononuclear cells, as well as tumor response to treatment." (PMID 40510149, 2025). "Niraparib significantly increased γ-H2AX positive staining in BMNCs compared with the control and tumor groups." (PMID 39739292, 2025). "Previous reports have highlighted the phosphorylated form, γ-H2AX, in PDAC associating it with aggressive tumor biology and poor prognosis." (PMID 41007761, 2025). "In vivo, the combination therapy achieved more than 74% tumour growth inhibition (p < 0.0001), accompanied by increased tumour cell death, reduced Ki‐67 expression and elevated γ‐H2AX levels." (PMID 41328625, 2025). "The group demonstrated that HMGB1 expression correlates with γ-H2AX expression, a key marker of DNA damage in tumor cells after RT, highlighting the interplay between HMGB1 and RT-induced DNA damage in cancer cells." (PMID 41332426, 2025). "H2AX, an isoform of histone H2A, is phosphorylated in response to nuclear DNA damage and plays roles in DNA repair, recombination, and tumor suppression." (PMID 40943373, 2025).
tumor (continued). "Intense γ‐H2AX and 8‐OHdG expression was observed in the cytoplasm and nuclei of poorly differentiated neoplastic cells, especially in small tumour islands in tumour aggressive samples." (PMID 40569274, 2025). "Functional studies demonstrated that RPGRIP1L knockdown reduced genomic instability in tumor cells, as evidenced by decreased Phosphorylated Histone H2AX (γH2AX) expression, and suppressed tumor growth in mouse models." (PMID 41469586, 2025). "This suggests a dual role for radiolabeled IMPY as a tumor-targeting tracer and as a therapeutic agent capable of eliciting cellular responses such as γ-H2AX formation, which is indicative of DNA damage." (PMID 40566582, 2025). "A well-established mechanism of cisplatin is to induce double-strand DNA damage in tumor cells, which can be detected using γ-H2AX as a specific marker." (PMID 41408324, 2025). "Correlation between tumor expression of Trop-2 and DNA damage stemming from the arrest of topoisomerase I on DNA, as measured by the DNA damage marker γ-H2AX, would indicate payload release." (PMID 39112464, 2024). "To further assess the effects of increased tumor oxygenation on the treatment of human RC with radiotherapy, we performed immunohistochemistry staining for γ-H2AX, a marker of DNA double-stranded breaks." (PMID 39007350, 2024). "While a moderate decrease was noted in PSMA and CD31 expression, significantly higher staining of γ-H2AX was observed in the treated tumor tissues compared to control untreated tumors, suggesting DNA double-strand damage by α-particle-emitting 225Ac-L1." (PMID 39324008, 2024). "Conversely, miR-125a-5p inhibited tumor growth by increasing rH2AX levels and decreasing H2AX levels." (PMID 39224810, 2024). "This indicates the possibility that tumors exhibiting high levels of γ-H2AX expression are likely to have a more invasive growth pattern and, indirectly, more advanced tumor stages." (PMID 38502354, 2024). "Consistent with our previous findings, the number of γ-H2AX foci, a marker for double-stranded DNA breaks and DNA damage, was increased in tumor cells under HDS conditions." (PMID 39261338, 2024). "H2AX contributes to the control of the cell cycle and to genomic stability and it has been proposed as a tumour suppressor and the gene locus was found deleted in a variety of cancers." (PMID 38402225, 2024). "For in vitro and in vivo tumor models, combination trastuzumab and cetuximab pre-treatment increased DNA damage (increased phospho-γ H2AX and decreased Rad51) and decreased tumor hypoxia." (PMID 38355949, 2024). "Immunohistochemical analysis determined an increased phosphorylation of H2AX in tumor tissues treated with the drugs, symptomatic of the production of DNA double-strand damage." (PMID 39203369, 2024). "Both normal and tumor tissue were examined for γ-H2AX, p16, and Lgr5-GFP expression through immunostaining." (PMID 39410012, 2024). "Both compounds significantly increased the expression levels of γ-H2AX in the tumor cells, induced DNA damage, reduced PARP levels, and impaired the DNA damage repair process in the tumor cells, ultimately leading to apoptosis." (PMID 39598828, 2024). "After radiotherapy at a dose of 6 Gy was performed on a murine model, immunostaining of γ-H2AX in the resected tumor tissues was conducted." (PMID 38994026, 2024). "In the mouse tumor tissue, IF showed higher γ-H2AX expression in the P4 + niraparib group compared with niraparib alone." (PMID 38798714, 2024). "An IHC assay indicated that PIK3R1 levels were decreased and γ-H2AX levels were increased, accompanied by tumor growth repression, after circPLPP4-ASO#1 application in the PDX-2 model." (PMID 38184597, 2024). "Taken together, our findings suggest that NPAS2 binds to and enhances the stability of H2AX mRNA, thereby decreasing the sensitivity of tumor cells to chemotherapy by augmenting DNA damage repair." (PMID 38291048, 2024).